FOXK1 (forkhead box K1)
Description:
Transcriptional regulator involved in different processes such as glucose metabolism, aerobic glycolysis, muscle cell differentiation and autophagy (By similarity). Recognizes and binds the forkhead DNA sequence motif (5'-GTAAACA-3') and can both act as a transcription activator or repressor, depending on the context. Together with FOXK2, acts as a key regulator of metabolic reprogramming towards aerobic glycolysis, a process in which glucose is converted to lactate in the presence of oxygen (By similarity). Acts by promoting expression of enzymes for glycolysis (such as hexokinase-2 (HK2), phosphofructokinase, pyruvate kinase (PKLR) and lactate dehydrogenase), while suppressing further oxidation of pyruvate in the mitochondria by up-regulating pyruvate dehydrogenase kinases PDK1 and PDK4 (By similarity). Probably plays a role in gluconeogenesis during overnight fasting, when lactate from white adipose tissue and muscle is the main substrate (By similarity). Involved in mTORC1-mediated metabolic reprogramming: in response to mTORC1 signaling, translocates into the nucleus and regulates the expression of genes associated with glycolysis and downstream anabolic pathways, such as HIF1A, thereby regulating glucose metabolism (By similarity). Together with FOXK2, acts as a negative regulator of autophagy in skeletal muscle: in response to starvation, enters the nucleus, binds the promoters of autophagy genes and represses their expression, preventing proteolysis of skeletal muscle proteins (By similarity). Acts as a transcriptional regulator of the myogenic progenitor cell population in skeletal muscle (By similarity). Binds to the upstream enhancer region (CCAC box) of myoglobin (MB) gene, regulating the myogenic progenitor cell population (By similarity). Promotes muscle progenitor cell proliferation by repressing the transcriptional activity of FOXO4, thereby inhibiting myogenic differentiation (By similarity). Involved in remodeling processes of adult muscles that occur in response to physiological stimuli (By similarity). Required to correct temporal orchestration of molecular and cellular events necessary for muscle repair (By similarity). Represses myogenic differentiation by inhibiting MEFC activity (By similarity). Positively regulates Wnt/beta-catenin signaling by translocating DVL into the nucleus. Reduces virus replication, probably by binding the interferon stimulated response element (ISRE) to promote antiviral gene expression. Accessory component of the polycomb repressive deubiquitinase (PR-DUB) complex; recruits the PR-DUB complex to specific FOXK1-bound genes. Acts as an indirect positive regulator of ferroptosis following phosphorylation by isoform Beta-II of PRKCB by promoting expression and subsequent secretion of LGALS13.
Synonyms: IMAGE:5164497; FOXK1L
Tractability: PROTAC: ubiquitination databases record sites on it; its protein half-life has been measured.
Target class: Transcription factor
Gene: Protein-coding gene on chromosome 7 (4,682,295 to 4,771,442, forward strand). Ensembl gene ENSG00000164916.
Subcellular location: Nucleus; Cytoplasm
Subcellular location (Human Protein Atlas): Nucleoplasm; Nucleoli fibrillar center
Pathways (Reactome):
Metabolism of proteins: UCH proteinases
Gene Ontology:
Molecular function: 14-3-3 protein binding; DNA-binding transcription factor activity; DNA-binding transcription repressor activity, RNA polymerase II-specific; protein binding; sequence-specific double-stranded DNA binding; transcription cis-regulatory region binding; DNA-binding transcription factor activity, RNA polymerase II-specific; RNA polymerase II cis-regulatory region sequence-specific DNA binding; DNA binding; RNA polymerase II transcription regulatory region sequence-specific DNA binding; sequence-specific DNA binding
Biological process: canonical glycolysis; intracellular glucose homeostasis; negative regulation of autophagy; negative regulation of DNA-templated transcription; positive regulation of DNA-templated transcription; regulation of glucose metabolic process; response to starvation; regulation of transcription by RNA polymerase II; negative regulation of transcription by RNA polymerase II; regulation of DNA-templated transcription
Cellular component: cytoplasm; nucleoplasm; nucleus; chromatin
Genetic constraint (gnomAD): Loss-of-function variants: 19 observed, 42.01 expected, observed/expected ratio (o/e) 0.45, 90% interval 0.31 to 0.66. The synonymous counts are far from expectation, so gnomAD's model fits this gene poorly and the ratio says little. Missense variants: 870 observed, 883.3 expected, observed/expected ratio (o/e) 0.98, 90% interval 0.93 to 1.04. Synonymous variants: 537 observed, 436.95 expected, observed/expected ratio (o/e) 1.23, 90% interval 1.14 to 1.32.
Homologues: Orthologues: chimpanzee FOXK1 (99% identical), macaque FOXK1 (99% identical), pig FOXK1 (90% identical), dog FOXK1 (90% identical), mouse Foxk1 (88% identical), rat Foxk1 (88% identical), guinea pig FOXK1 (72% identical), rabbit FOXK1 (70% identical), zebrafish foxk1 (61% identical). Paralogues in human: FOXK2 (49% identical), FOXJ3 (13% identical), FOXN1 (13% identical), FOXC1 (13% identical), FOXC2 (13% identical), FOXD1 (13% identical), FOXD4L1 (13% identical), FOXJ1 (12% identical), FOXD3 (12% identical), FOXI3 (12% identical), FOXD4 (12% identical), FOXD2 (12% identical), and 29 more.
Diseases named in the same sentence as FOXK1 in open-access papers:
FOXK1 is named in the same sentence as 64 diseases in open-access papers, as found by Europe PMC text mining. Sharing a sentence is not in itself a finding about the gene and the disease. The quoted sentences say what the papers report.
colorectal cancer (33 papers, 2016 to 2025). A primary or metastatic malignant neoplasm that affects the colon or rectum. "In bladder cancer for instance, the miR-4492/ROMO1 axis controls the proliferation, migration, and invasion of cancer cells, while the miR-4492/FOXK1 axis has been implicated in the proliferation and invasion of colorectal cancer cells." (PMID 38261743, 2024). "For instance, in colorectal cancer, the downregulation of tRF‐3008A, which is derived from tRNA‐Val, disrupted the stability of FOXK1, a positive regulator of the Wnt/β‐catenin pathway, in an AGO‐dependent manner, thereby inhibiting metastasis and progression." (PMID 39993386, 2025). "The univariable analysis showed that increased levels of CA19-9, XIST, and FOXK1, as well as decreased levels of TSIX and miRNA-497, were linked to a greater risk of colorectal cancer (CRC)." (PMID 40032945, 2025). "Recent studies in colorectal cancer revealed that a tRF from tRNAVal, which impairs FOXK1 mRNA stability and inhibits the Wnt/β-catenin pathway in an AGO-dependent manner, inhibited colorectal cancer cell proliferation and metastasis." (PMID 36797764, 2023). "Further, tRF3008A attenuates progression of colorectal cancer by destabilizing Forkhead Box K1 (FOXK1) in an Argonaute (AGO)-dependent manner." (PMID 37139153, 2023). "Downregulation of the FoxK1 gene can induce G0/G1 cell cycle arrest in colorectal cancer cells, inhibit the growth of colorectal cancer cells, promote apoptosis, and increase cell sensitivity to 5-fluorouracil (5-FU) induced apoptosis." (PMID 35903069, 2022). "tRF3008A suppresses the metastasis and progression of colorectal cancer by destabilizing FOXK1 in an AGO-dependent manner." (PMID 35065674, 2022). "A good deal of circRNA/miRNA/mRNA regulatory networks have been unraveled in human cancers, like circAPLP2/miR-485-5p/FOXK1 in colorectal cancer and circMYLK/miR-513a-5p/VEGFC in renal cell carcinoma." (PMID 34287578, 2021). "It was described that miR-4492 targets forkhead box K1 (FOXK1), an oncogene that regulates proliferation and invasion in colorectal cancer cells." (PMID 33003646, 2020). "Overexpressed LINC01503 regulates forkhead box K1 (FOXK1) expression by competing with miR-4492, which promotes cell proliferation and invasion in colorectal cancer." (PMID 32117736, 2020). "Preliminary studies have investigated the roles of FOXK1 in ovarian cancer, colorectal cancer, and glioblastoma, but the role of FOXK1 in GC has been less studied." (PMID 32268297, 2020). "LINC01503 was reported to promote colorectal cancer cell proliferation and invasion by regulating the miR-4492/FOXK1 signaling." (PMID 32938459, 2020). "FOXK1 was highly expressed in colorectal cancer, and FOXK1 and FOXK2 transfered DVL (Dishevelled)-related proteins into the nucleus, which positively regulated Wnt/β-catenin signaling pathway." (PMID 30744670, 2019). "For example, in colorectal cancer, FOXK1 acts as a DVL-interacting protein, and transfers DVL-related proteins into the nucleus with FOXK2, which positively regulates the Wnt/β-catenin signaling pathway." (PMID 30744670, 2019). "Upregulation of FOXK1 has been detected in several types of human cancers including gastric, gallbladder, and colorectal cancers, and high expression of FOXK1 may lead to poor prognosis in different types of cancers." (PMID 37173384, 2023). "Moreover, we found that tRF3008A binds to AGO, resulting in repressed expression of FOXK1, thereby suppressing progression of colorectal cancer cells." (PMID 35065674, 2022). "Colorectal cancer is influenced by both FoxK1 and FoxK2, with they all promoting the tumor." (PMID 35903069, 2022). "Interestingly, our findings reveal that FOXK1 mRNA is a predominant binding target for tRF3008A in colorectal cancer cells." (PMID 35065674, 2022). "FoxK1 is highly expressed in colorectal cancer cells and tissues." (PMID 35903069, 2022).
colorectal cancer (continued). "In addition, experimental results have also shown that up-regulation of FoxK1 can reverse the inhibitory effect of miR-497-5p on proliferation, anti-apoptotic activity, and metastasis of colorectal cancer cells." (PMID 35903069, 2022). "Recent studies have also shown that tRF3008A suppresses the progression and metastasis of colorectal cancer by destabilizing FOXK1 in an AGO-dependent manner, while tRF-3001b aggravates the development of nonalcoholic fatty liver disease by inhibiting autophagy via the same mechanism." (PMID 36035226, 2022). "Besides, miR‐4492 is significantly downregulated in meningioma cells and its silencing has shown to inhibit FOXK1 expression and promote colorectal cancer proliferation." (PMID 33252831, 2021). "Previous evidence had indicated that FOXK1 acts as a tumor oncogene in colorectal cancer." (PMID 27882939, 2016). "In the present study, we found that FOXK1 is highly expressed in 16 types of solid tumor tissues and that increased FOXK1 expression significantly correlated with progression, metastasis, and poor outcome in patients with colorectal cancer (CRC)." (PMID 27223064, 2016). "Moreover, FOXK1 has been found to high express in multiple cancers, such as colorectal carcinoma." (PMID 29050292, 2017). "It is suggested that the interaction between FoxK1 and FHL2 promotes the growth and metastasis of colorectal cancer cells." (PMID 35903069, 2022). "For instance, FOXK1 and FOXK2 were shown to induce nuclear translocation of DVL and to activate WNT/β-catenin signaling in colorectal cancer." (PMID 35349489, 2022). "However, the role of FOXK1 in the progression of colorectal cancer (CRC) remains unknown." (PMID 27223064, 2016). "And in colorectal cancer, knockdown FHL2 repressed the FOXK1-dependent cell growth and metastasis." (PMID 33092075, 2020). "We recently found that FOXK1 was overexpressed in 16 cancerous human tissue types (including gastric cancer (GC)), induced tumor cell EMT, maintained the invasive potential of colorectal cancer and appeared to have a crucial role in the metastatic progression of human carcinomas." (PMID 27882939, 2016). "However, the effects of the interaction of FOXK1 and FHL2 on the development, progression and prognosis of colorectal cancer (CRC) remain to be defined." (PMID 27892920, 2016). "DLC-1 is a Rho GTPase-activating protein (RhoGAP), could facilitate melanoma cell invasion and metastasis by cooperating transcription factor FOXK1 to promote MMP9 expression and enhancing colorectal cancer metastasis by the epithelial-to-mesenchymal transition." (PMID 33682883, 2021).
gastric cancer (23 papers, 2009 to 2025). A primary or metastatic malignant neoplasm involving the stomach. "A study also affirms that FOXK1 restrains autophagy in gastric cancer via mediating myc-associated zinc lipoprotein in acidic microenvironment." (PMID 35220908, 2022). "In gastric cancer, c-Jun directly regulates FOXK1, promoting cell proliferation, invasion, and metastasis." (PMID 40092686, 2025). "FoxK1 can physically interact with and stabilize vimentin, and FoxK1 positively correlates with vimentin expression in gastric cancer cells." (PMID 35903069, 2022). "Of note, FOXK1 has been indicated to facilitate gastric cancer cell growth, EMT, invasion, and metastasis by transcriptionally activating c-jun." (PMID 34095464, 2021). "For instance, FOXK1 interacts with and stabilises vimentin, thereby promoting gastric cancer cell migration and metastasis via the induction of EMT." (PMID 33757532, 2021). "Taken together, these data clarify that the FOXK1/MAZ axis can represent an effective therapeutic target for regulating autophagy to reverse gastric cancer EMT progression in an acidic microenvironment." (PMID 32268297, 2020). "Expression of miR-646 has been shown to directly regulate CDK6 and FOXK1 expression in gastric cancer, suggesting its utility as a potential therapeutic target." (PMID 32344635, 2020). "In gastric cancer, forkhead box K1 (FOXK1) is a transcription factor involved in cancer development." (PMID 33194736, 2020). "MiR‐646 also inhibited cell proliferation and EMT‐induced metastasis by targeting FOXK1 in gastric cancer." (PMID 32347652, 2020). "However, in gastric cancer, their roles diverge: Foxk1 promotes epithelial‐mesenchymal transition, migration and invasion in vitro, while Foxk2 functions antagonistically." (PMID 39789420, 2025). "Similarly, an analysis of gastric cancer samples revealed increased expression of FOXK1 in tumor tissue compared to normal tissue." (PMID 37174744, 2023). "In addition, the co-expression of FoxK1 and vimentin promotes the metastasis of gastric cancer cells by inducing EMT." (PMID 35903069, 2022). "FoxK1 overexpression enhances gastric cancer cells proliferation, migration, and invasion." (PMID 35903069, 2022). "In addition, miR-646 targets FOXK1 to significantly inhibit cell proliferation and epithelial-mesenchymal transition in gastric cancer." (PMID 35022405, 2022). "Interestingly, FoxK1/2 play different roles in gastric cancer, FoxK1 promoting and FoxK2 inhibiting it." (PMID 35903069, 2022). "Recently report indicates that FOXK1 regulates EMT in gastric cancer (GC)." (PMID 29050292, 2017). "In gastric cancer cells, a TGF-β-induced increase in proliferation, migration, EMT, and metastatic potential was found to be dependent upon the upregulation of FOXK1 by c-jun." (PMID 37174744, 2023). "For example, it binds and activates human FOXK1 (Forkhead box (FOX) K1) gene promoter, enhancing proliferation and metastasis in gastric cancer." (PMID 36476606, 2022). "For example, the study found that the coexpression of FOXK1 and Vimentin enhanced cell metastasis through the induction of EMT in gastric cancer cells." (PMID 35281866, 2022). "The inhibition of FOXK1 in an acidic microenvironment triggers autophagy and reverses EMT in gastric cancer cells." (PMID 33194736, 2020). "To further verify the high expression of FOXK1 in GC, we subjected 60 GC tissues and their adjacent tissues, which included 31 tissues of nonmetastatic gastric cancer (NmGC) and 29 primary metastatic gastric cancer tissues (mGC), to immunohistochemical staining (IHC)." (PMID 32268297, 2020). "The genes PLA2G4A, BMP5, MMP6, KNNMB4 and DYM were candidates for the GP202 gastric cancer cell line and the genes TXNL4B, FOXK1, PTPRJ, and SNN were candidates for the IPA220 gastric cancer cell line." (PMID 19563644, 2009).
gastric cancer (continued). "An investigation of the functions of FOXK1 in human cancers revealed that it promoted proliferation, EMT, invasion, and metastasis across multiple human cancers, including glioma, ovarian cancer, gastric cancer, and CRC." (PMID 37174744, 2023). "However, whether FOXK1 expression contributes to gastric cancer (GC) development and progression remains unknown." (PMID 27882939, 2016).